ATM (ATM serine/threonine kinase)
Diseases named in the same sentence as ATM in open-access papers (continued):
Sharing a sentence is not in itself a finding about the gene and the disease.
Stroke (2 papers, 2023 to 2025). Sudden impairment of blood flow to a part of the brain due to occlusion or rupture of an artery to the brain.
synovial sarcoma (2 papers, 2023 to 2026). "The most common molecular alterations (excluding canonical SS18::SSX fusions in synovial sarcoma) involved ATM (18%), ARID1A (9%), CTNNB1 (9%), PALB2 (9%), and NF1 (9%), while 46% of profiled cases showed no detectable alterations." (PMID 41504936, 2026).
testicular cancer (2 papers, 2020 to 2021). A primary or metastatic malignant neoplasm that affects the testis. "Knocking down ASH2L in these cells and in the NT2D1 testicular cancer cell line rendered them resistant to bleomycin, etoposide, and cisplatin but did not affect their sensitivity toward ATM or ATR inhibitors." (PMID 33257682, 2020).
Acidosis (1 paper, 2021). Abnormal acid accumulation or depletion of base. "Acidosis had little effect on cyclin-dependent kinase (CDK) or casein kinase 2 activity, two members of the CMGC family, or Ataxia telangiectasia mutated (ATM)/ATM and RAD3-related (ATR) activity, but reduced the phosphorylation of MAPK/CDK substrates." (PMID 34113235, 2021).
ADULT syndrome (1 paper, 2010). "Interestingly, the ADULT syndrome R298Q DNA-binding domain mutant, previously reported to enhance ΔNp63γ TA2-dependent transcription through an intramolecular mechanism, stimulated the ATM promoter 1.3-fold relative to wild-type ΔNp63α." (PMID 20663147, 2010).
Age-related cataract (1 paper, 2022). A type of cataract (opacification of the lens) that forms during the course of aging.
AIDS (1 paper, 2008). A syndrome resulting from the acquired deficiency of cellular immunity caused by the human immunodeficiency virus (HIV). "At least three kinases of the phosphatidylinositol 3-kinase family, namely ATM, mTOR and DNA-dependent protein kinase (DNA-PK), operate at two different levels of AIDS pathogenesis." (PMID 18560558, 2008). "Although long-term pharmacological inhibition of ATM might have deleterious oncogenic side effects, the therapeutic effect of short-term inhibition of ATM should be evaluated in AIDS." (PMID 18560558, 2008).
amenorrhea (1 paper, 2023). The absence of menses in a woman who has achieved reproductive age. "The association of gBRCApv with amenorrhea risk is biologically plausible as BRCA genes play essential roles in ATM‐mediated repair of DNA double strand breaks." (PMID 37698031, 2023).
anal squamous cell carcinoma (1 paper, 2023). A squamous cell carcinoma (SCC) arising from the anal canal or the anal margin (perianal skin).
aortic stenosis (1 paper, 2022). Aortic valve stenosis is a aortic valve disease caused by the incomplete opening of the aortic valve. "Our studies on cardiac biopsies from severe aortic stenosis with patients with HFpEF-like syndrome further supported these findings, highlighting the involvement of both ATR/CHK1 and ATM/CHK2 axis." (PMID 35811699, 2022).
appendiceal adenocarcinoma (1 paper, 2017).
biliary tract cancer (1 paper, 2022). "DDR genes such as breast cancer susceptibility gene 1/2 (BRCA 1/2), ataxia-telangiectasia mutated (ATM), and BRCA1-associated protein 1 (BAP1) were identified germline or somatic inactivation in 63.5% biliary tract cancer patients." (PMID 36226174, 2022).
bone metastasis (1 paper, 2025). Transfer of a neoplasm from its primary site to bones. "Logistic regression analysis showed that ATM expression, as well as the presence of bone metastasis and the absence of liver metastasis, was significantly associated with a response to treatment (p = 0.006; OR: 0.06; 95% CI: 0.008–0.45)." (PMID 40310425, 2025).
brainstem glioma (1 paper, 2022). "One treatment strategy under preclinical investigation for brainstem gliomas is to inhibit the function of ataxia–telangiectasia mutated kinase (ATM), a master regulator of the cellular response to radiation therapy." (PMID 36139666, 2022). "We use genetic tools to test if ATM inactivation can enhance the efficacy of radiation therapy in this Pten-mutated brainstem glioma model." (PMID 36139666, 2022). "We next sought to examine whether loss of ATM can radiosensitize brainstem gliomas driven by Pten loss." (PMID 36139666, 2022). "Specifically, we generated a primary mouse model of brainstem gliomas driven by Pten loss and examined whether ATM inactivation can cause radiosensitization." (PMID 36139666, 2022). "Here we used genetically engineered mice to determine whether brainstem gliomas harboring PTEN loss-of-function alterations can be radiosensitized by deletion of ATM." (PMID 36139666, 2022). "Here, we sought to determine if ATM inactivation could radiosensitize a primary mouse model of brainstem glioma driven by Pten loss." (PMID 36139666, 2022). "Thus, an important open question is whether ATM loss radiosensitizes brainstem gliomas of different genotypes that also harbor H3K27M." (PMID 36139666, 2022). "Future work with improved complex mouse strains and/or improved viral constructs will be needed to address the effects of ATM inactivation and radiation therapy on different genotypes of brainstem gliomas containing H3K27M." (PMID 36139666, 2022). "We find that ATM inactivation does not enhance the efficacy of radiation therapy for this model of Pten-mutated brainstem glioma." (PMID 36139666, 2022).
brainstem tumors (1 paper, 2022). "We infected NestinTVA, PtenFL/FL, and AtmFL/FL (nPtenA FL/FL) mice with the RCAS viruses to initiate brainstem tumors in which both alleles of ATM are deleted." (PMID 36139666, 2022). "As controls, we infected littermate NestinTVA, PtenFL/FL, and AtmFL/+ (nPtenA FL/+) mice with the same RCAS viruses to initiate brainstem tumors that retained expression of ATM." (PMID 36139666, 2022).
breast adenocarcinoma (1 paper, 2021).
carcinosarcoma (1 paper, 2025). A malignant tumor composed of a mixture of carcinomatous and sarcomatous elements. "One recently published report on carcinosarcoma of the uterus identified an NF2 mutation alongside an ATM mutation; further information on the prevalence of NF2 in carcinosarcoma is needed." (PMID 40862839, 2025).
cerebral thrombosis (1 paper, 2024). "This susceptibility to thrombosis, previously reported in AT patients as a notable frequency of cerebral thrombosis, may result from NOX-2 related clotting and platelet activation; further study is, however, necessary to deeper analyze the effect of ATM on the two systems." (PMID 39326070, 2024).
cervical adenocarcinoma (1 paper, 2026). An adenocarcinoma arising from the cervical epithelium.
cervical squamous cell carcinoma (1 paper, 2023). A squamous cell carcinoma arising from the cervical epithelium. "The results showed that compared with the control group of cervical squamous cell carcinoma SiHa cells, the expression of differential proteins PCNA, ATM, LIG1 and HMGB1 in Ect1/E6E7 cells decreased significantly, while the expression of TDG and OGG1 proteins increased significantly." (PMID 36726132, 2023).
Chlamydia infection (1 paper, 2025). "Chlamydia infection disturbs the DDR by preventing the recruitment of p-ATM and 53BP1 to damaged sites." (PMID 40008889, 2025).
cognitive diseases (1 paper, 2020). "We also summarise recent evidence on ATM implication in neurological and cognitive diseases beyond A-T, bringing out ATM as new pathological substrate and potential therapeutic target." (PMID 32858941, 2020).
colorectal NETs (1 paper, 2012). "Relationships between ATM protein expression and various clinicopathologic factors in colorectal neuroendocrine tumors." (PMID 22485171, 2012). "Hence, a clinical research with PARP inhibitor in ATM-negative colorectal NETs should be actively implemented in Asian countries." (PMID 22485171, 2012).
cutaneous squamous cell carcinoma (1 paper, 2016). "al., showed that both ATR and ATM are highly mutated (30–35%) in cutaneous squamous cell carcinoma which is mostly associated with UV exposure." (PMID 27442013, 2016).
cystic kidney (1 paper, 2021). "In this regard, we speculated whether inhibition of either ATR or ATM could further increase genomic instability in cystic kidney epithelial cells, leading to cell death." (PMID 33802342, 2021).
diabetic foot ulcer (1 paper, 2026). "ATM-deficient fibroblasts show reduced proliferation and impaired DNA repair, suggesting a role for ATM in tissue regeneration; in a diabetic foot ulcer mouse model, restoring ATM expression by inhibiting miR-200 improved wound healing outcomes." (PMID 41511357, 2026).
diabetic nephropathy (1 paper, 2020). "Furthermore, miR-146a plays an anti-inflammatory role in the context of diabetic nephropathy (DN), and miR-18a-5p modulates autophagy by regulating the ataxia telangiectasia mutated (ATM) gene, which may be prophylactic or therapeutic in the context of DN." (PMID 33299464, 2020).
diffuse midline glioma (1 paper, 2025). A diffuse glioma that arises from the midline structures of the central nervous system. "Our work provides insight into mechanisms of resistance and biomarkers required to design future trials of ATM inhibitors in diffuse midline glioma patients." (PMID 40244686, 2025).
dysplasia (1 paper, 2022). A usually neoplastic transformation of the cell, associated with altered architectural tissue patterns. "A 2016 study showed that ATM (ATM serine/threonine kinase) expression was found in 77.8% of progressive dysplasia and 49.4% of static dysplasia, and that yH2AFX expression was observed more in progressive OPLs (55.6%) than in static OPLs (23.5%)." (PMID 35326482, 2022).
E. coli infection (1 paper, 2020). "In response to the DSBs generated upon pathogenic E. coli infection, host activates phosphorylation of Cdc25 through ATM-Chk2 pathway to hamper cell cycle progression." (PMID 32223892, 2020).
EBVinfection (1 paper, 2010). "The initiation of cell proliferation defines the period after EBVinfection when ATM and Chk2 were active in suppressing transformation." (PMID 21147465, 2010). "Corroborating our findings ofγ-H2AX activation, EBV infection induced additional hallmarks of the DDRincluding auto-phosphorylation of the H2AX kinase ATM (pATM Ser1981), andpunctate localization of the damage adaptor 53BP1." (PMID 21147465, 2010).
endometrial ovarian cancer (1 paper, 2024).
endometrial stromal sarcoma (1 paper, 2024). "Few studies have investigated ATM, BLM, and CDH1 gene mutations in high-grade endometrial stromal sarcoma." (PMID 39009979, 2024).
endometrial tumor (1 paper, 2022). "In this patient, with an endometrial tumor diagnosed at age 53 and loss of MLH1/PMS2 expression, we identified two variants classified as pathogenic and likely pathogenic in the ATM and ST18 genes, respectively." (PMID 36077770, 2022).
familial hypocalciuric hypercalcemia (1 paper, 2024). Familial hypocalciuric hypercalcemia (FHH) is a generally asymptomatic genetic disorder of phosphocalcic metabolism characterized by lifelong moderate hypercalcemia along with normo- or hypocalciuria and elevated plasma parathyroid hormone (PTH) concentration. "One patient (MEN1 c.526G > T) associated PHEO and familial hypocalciuric hypercalcemia, and 2 other had PHEO and idiopathic hypercalcemia (RB2 c.644C > T), respectively, primary hyperparathyroidism (ATM c.5639C > T)." (PMID 39673085, 2024).
gliomatosis (1 paper, 2020). "Based on preoperative MRI, the involvement of the SVZ (9 patients, 90.0%) and the presence of gliomatosis (6 patients, 60.0%) were frequently observed in the ATM mut(+) group." (PMID 32736562, 2020). "Interestingly, although well-known poor prognostic factors, such as either the presence of gliomatosis or the involvement of the SVZ, were predominant in the ATM mut(+) group, we observed excellent in-field control without in-field failure." (PMID 32736562, 2020).
gliosarcoma (1 paper, 2020). A rare histological variant of glioblastoma (WHO grade IV) characterized by a biphasic tissue pattern with alternating areas displaying glial and mesenchymal differentiation (WHO). "Based on the trace VAF of GRIN2A mutation in the initial gliosarcoma and on the absence of ATM mutation in the frontal recurrence, the initial tumor most likely contained few genetically distinct subpopulations that gave rise to the various subsequent tumors." (PMID 32014051, 2020).
goblet cell adenocarcinomas (1 paper, 2023). "ATM gene mutations are present in appendiceal goblet cell adenocarcinomas, mucinous adenocarcinomas of the appendix, low- and high-grade appendiceal mucinous neoplasms, and well-differentiated neuroendocrine tumors of the appendix." (PMID 37509254, 2023).
Gorlin syndrome (1 paper, 2014). "Therefore, ATM and Gorlin syndrome patients share molecular deficits associated with both retinoic acid and ATM pathways." (PMID 28250390, 2014).
Gynecomastia (1 paper, 2020). Abnormal development of large mammary glands in males resulting in breast enlargement. "ATM, BRCA1, PALB2, RAD51B, and XRCC3 promoter methylation levels were evaluated in paired tumor, normal tissue, and adjacent lymph nodes, and in gynecomastia tissue samples." (PMID 32295201, 2020). "Among the five gene promoters tested, only two - RAD51B and XRCC3—disclosed statistically significant differences between tumor and gynecomastia tissue samples, whereas ATM, BRCA1, and PALB2 did not." (PMID 32295201, 2020).
hemochromatosis (1 paper, 2018). A disorder of iron metabolism characterized by a triad of HEMOSIDEROSIS; LIVER CIRRHOSIS; and DIABETES MELLITUS. "Examples are mitogen-activated protein kinase (MAPK)/RAS family members (HRAS and NRAS), hemochromatosis (HFE), BRD7, ATM, vimentin (VIM), which are upregulated in poorly differentiated cell lines and in human HCC datasets." (PMID 30176945, 2018).
hemophilia A (1 paper, 2014). The most common form of hemophilia characterized by spontaneous or prolonged hemorrhages due to factor VIII deficiency. "The susceptibility of many disease genes (such as DMD, ATM, NPC1 (Niemann-Pick disease), F9 (hemophilia A), F8 (hemophilia B)) to aberrant pre-mRNA splicing has spawned creative therapeutic approaches that have been the focus of a great deal of time and effort." (PMID 24456648, 2014).
high-grade glioma (1 paper, 2025).
human papillomavirus infection (1 paper, 2024). "The upregulated genes (n = 135) included ATM, COL1A1, FN1, ITGA6, and LAMB1, which were found to be enriched in pathways related to human papillomavirus infection and herpes simplex virus 1 infection." (PMID 40226717, 2024).
hypospadias (1 paper, 2022). Hypospadias is the displacement of the urethral meatus on the ventrum of the penis. "Thus, the relevance of ATM to hypospadias CAVD needs to be verified more thoroughly." (PMID 36437957, 2022).
infarction (1 paper, 2023). A localised pathological necrosis of tissue resulting from obstruction of the blood supply usually by a thrombus, an embolus, or vascular torsion. "Based on these studies, ATM inhibition diminished cardiac inflammation, remodeling, and dysfunction 1–7 days postmyocardial infarction, whereas aggravating cardiomyocyte apoptosis, fibrosis, and cardiac hypertrophy was 14–28 days postmyocardial infarction." (PMID 36156462, 2023).
influenza (1 paper, 2025). An acute viral infection of the respiratory tract, occurring in isolated cases, in epidemics, or in pandemics; it is caused by serologically different strains of viruses (influenzaviruses) designated A, B, and C, has a 3-day incubation period, and usually lasts for 3 to 10 days. "We found that the ATM inhibitor KU‐60019 and CK2 inhibitor CX‐4945 significantly inhibit influenza A and B viral replication in both cells and mice, albeit slightly less effectively than the well‐known antiviral drug Oseltamivir." (PMID 39575547, 2025). "Secondly, the host kinases ATM and CK2 might serve as potential targets for developing anti‐viral drugs for influenza." (PMID 39575547, 2025).
insomnia (1 paper, 2022). A sleep disorder characterized by difficulty in falling asleep and/or remaining asleep. "Tumor suppressor genes, CMTM7, NKAPL and ATM (encoding ATM checkpoint kinase) may allude to aberrant DNA damage responses contributing to insomnia, and indeed, there are several reports of links between DNA damage and sleep in the literature." (PMID 35711912, 2022).
intervertebral disc degeneration (1 paper, 2020). "Attenuation of ATM signaling mitigates disc cellular senescence and intervertebral disc degeneration." (PMID 32567210, 2020).
Japanese encephalitis (1 paper, 2013). A disease due to a virus transmitted by an arthropod). "To conclude, a young boy presenting with ATM in an endemic region of JE, then a possibility of Japanese encephalitis, should be sought by clinicians as early use of immunomodulator shows survival benefit." (PMID 23585973, 2013).
large cell carcinoma (1 paper, 2023). A malignant epithelial neoplasm composed of large, atypical cells.